MC5R (melanocortin 5 receptor)
Diseases named in the same sentence as MC5R in open-access papers:
MC5R is named in the same sentence as 51 diseases in open-access papers, as found by Europe PMC text mining. Sharing a sentence is not in itself a finding about the gene and the disease. The quoted sentences say what the papers report.
Obesity (8 papers, 2015 to 2024). Accumulation of substantial excess body fat. "MC5R mutations in Quebec families and Finns exhibit significant linkage or association with the obesity phenotype." (PMID 35955857, 2022). "The polymorphisms of MC5R are associated with obesity in humans." (PMID 36324508, 2022). "Single nucleotide polymorphisms in MC5R are associated with type 2 diabetes and obesity in Finns, suggesting that MC5R might be involved in glucose disposal in humans." (PMID 35955857, 2022). "In addition, MC5R expression down-regulates leptin secretion in cultured adipocytes and in humans MC5R polymorphisms were reported to be associated with obesity." (PMID 26029239, 2015). "Expression of MC1R, MC4R and MC5R has been suggested in the adipose tissue of human obese subjects and these receptors may reflect an aspect of the pathophysiology of human obesity." (PMID 26459134, 2015). "When developing an anti-obesity therapeutic drug with selective MC4R/MC5R properties, effects on lipolysis in white adipose tissue may be physiologically relevant." (PMID 26459134, 2015). "Therefore, MC5R is a potential target for treating patients with obesity and diabetes mellitus." (PMID 35955857, 2022). "Notably, ChrSd supplementation lowered the hepatic expression of genes previously reported to be candidate genes for obesity, such as Insig-1, lepR, neurotrophic tyrosine kinase receptor type 2 (Ntrk2), melanocortin 5 receptor (Mc5r), and matrix metallopeptidase 7 (Mmp7)." (PMID 27977712, 2016).
diabetes (4 papers, 2021 to 2024). "Our results demonstrated that PL-8331 therapy, a peptide that also targets MC1r and MC5r, effectively protected the eye from retinopathy associated with diabetes." (PMID 37108092, 2023). "Targeting MC1r and MC5r in the retina may be important in preventing damage and cell loss in the retina in uveitis, diabetes, and IRI." (PMID 38785932, 2024). "The possibility of targeting the MC1r and MC5r has been shown to reduce the retinopathy mediated by diabetes." (PMID 37108092, 2023). "To this regard, we have previously reported an emerging role of melanocortin receptors subtypes 1 and 5 (MC1R and MC5R), which when activated are able to counteract the retinal pro-inflammatory milieu induced by diabetes." (PMID 34603029, 2021).
diabetic retinopathy (4 papers, 2022 to 2024). "Conversely, treatment with PG20N, a highly selective antagonist of MC5R exacerbated diabetic retinopathy." (PMID 35721571, 2022). "Furthermore, in mice with STZ-induced diabetic retinopathy, intravitreal injection of the MC5R peptidomimetic agonist PG-901 attenuated, while MC5R antagonist PG20N augmented, retinal release of various inflammatory cytokines, such as IL-1α, IL-1β, IL-6, MIP-1α, MIP-2α, and MIP-3α." (PMID 35721571, 2022). "MC1R and MC5R agonists reduced anti-inflammatory cytokines and chemokines and enhanced manganese superoxide dismutase and glutathione peroxidase levels of retinal cells, indicating that MC1R and MC5R agonists exert a protective role on experimental diabetic retinopathy." (PMID 38397406, 2024). "However, MC5R is reported to protect from uveitis-derived retinal damage by regulating the activation of CD4+ regulatory T cells and to attenuate retinal degeneration in an experimental model of diabetic retinopathy." (PMID 37359372, 2023).
uveitis (4 papers, 2016 to 2025). An inflammatory process affecting a part of or the entire uvea. "Also, the regulatory immunity in uveitis can be mediated via MC5R and adenosine 2 A receptor (A2Ar)." (PMID 41002740, 2025). "Importantly, stimulation of the melanocortin-adenosinergic pathway may be possible in human uveitis patients because expression of MC5r and A2Ar was similar between uveitis patients and controls." (PMID 27886238, 2016). "In this study we show that MC5r and A2Ar have distinct roles in the recovery from EAU, and that MC5r expression on specific subsets of monocytes and A2Ar expression on CD4 T cells is similar between uveitis patients and healthy controls." (PMID 27886238, 2016).
autoimmune uveitis (3 papers, 2018 to 2025). An autoimmune form of uveitis (disease). "Recent studies have suggested that MC1R and MC5R can be therapeutic targets to suppress autoimmune uveitis." (PMID 41002740, 2025). "Moreover, it is these macrophages that expand in the spleen at the resolution of experimental autoimmune uveitis and are dependent on the expression of the α-MSH receptor MC5r." (PMID 30613828, 2018).
acne (2 papers, 2022 to 2023). An inflammatory process of the sebaceous glands which is characterized by comedones, nodules, papules and/or pustules on the skin. "Against this argument of MC5‐R involvement in acne is a more recent study." (PMID 37275429, 2023).
cardiac hypertrophy (2 papers, 2018 to 2024). "The beneficial effects of MC5R agonism on the cardiac hypertrophy caused by high glucose was also observed also by echocardiographic evaluations of rats made diabetics with streptozotocin (65 mg/kg i.p.)." (PMID 30416452, 2018). "To test for a regulatory role of MC5-R in cardiac hypertrophy, we engineered a tamoxifen-inducible cardiomyocyte-specific MC5-R KO mice (Mc5r-cKO) by crossing Mc5rfl/fl mice with Myh6-MCM transgenic mice." (PMID 38454158, 2024). "Conversely, silencing MC5-R signaling in cardiomyocytes aggravates pressure overload-induced cardiac hypertrophy and fibrosis." (PMID 38454158, 2024). "PI3K is a major player for mediating cardiac glucose since it is a regulator of glucose transporters, it is involved in reduction of cardiac hypertrophy, and it is stimulated by the MC5R after α-MSH activation in HEK293 cells." (PMID 30416452, 2018). "α-MSH is expressed in the heart and protects against pathological cardiac hypertrophy by activating MC5-R in cardiac myocytes, which may be a potential therapeutic target for the management of heart failure." (PMID 38454158, 2024). "Corroborating the regulatory role of MC5-R in cardiac remodeling, our loss-of-function study revealed that silencing MC5-R specifically in cardiomyocytes renders mice more susceptible to TAC-induced cardiac hypertrophy and fibrosis." (PMID 38454158, 2024). "Silencing of MC5-R in cardiomyocytes induced hypertrophy and fibrosis markers in vitro and aggravated TAC-induced cardiac hypertrophy and fibrosis in vivo." (PMID 38454158, 2024). "This has been done by using α-MSH and selective MC5R agonists and assessing the expression of GLUT4 and GLUT1 transporters, miR-133 and urotensin receptor levels as a marker of cardiac hypertrophy." (PMID 30416452, 2018). "Cardiac hypertrophy induced by Ang II infusion (for 2 or 4 weeks) did not however affect MC5-R protein level in the LV (Fig. EV3)." (PMID 38454158, 2024). "On the other hand, fibroblasts are considered as important effector cells in the hypertrophic response to Ang II and Mc5r-cKO mice were not sensitized to Ang II-induced cardiac hypertrophy." (PMID 38454158, 2024).
major depressive disorder (2 papers, 2022 to 2025). An episode of depression lasting two or more weeks without an intervening episode of mania. "Collaborative involvement of the MC1R, MC2R, and MC5R genes are implicated in the risk of major depressive disorder." (PMID 41002740, 2025). "Meanwhile, MC1R, MC2R, and MC5R genes are involved in the risk of major depressive disorder." (PMID 41002740, 2025). "The recent literature shows that three genes (MC1R, MC2R, and MC5R) increase the risk of major depressive disorder (MDD), and one gene (MC4R) is associated with an increased risk of type 2 diabetes, but its association needs to be researched further." (PMID 41002740, 2025). "Three melanocortin receptor genes (MC1R, MC2R, and MC5R) contribute to the risk of major depressive disorder (MDD), and one melanocortin receptor gene (MC4R) contributes to the risk of type 2 diabetes (T2D)." (PMID 35955479, 2022).
melanoma (2 papers, 2012 to 2020). A malignant, usually aggressive tumor composed of atypical, neoplastic melanocytes. "However, we could exclude the probable involvement of MC4R and MC5R, which are also present in B16-F10 melanoma cells." (PMID 31968661, 2020).
schizophrenia (2 papers, 2011 to 2013). A major psychotic disorder characterized by abnormalities in the perception or expression of reality. "Because MC5R's association with schizophrenia was identified against the genetic background of a risk allele for the immunomodulatory kynurenine pathway enzyme TDO2, it is most likely that the key action in this case would be the reported inhibition of IFNγ expression by MC5R." (PMID 23847488, 2013). "Such may be the case for the association between schizophrenia and a coding change in the MC5R gene identified in a temperate-zone genetic association study." (PMID 23847488, 2013). "The evolutionary trade-off in this case would have been an increased prevalence of polymorphisms in melanotropin genes (MCHR1, MC5R, MCHR2) of risk for schizophrenia." (PMID 23847488, 2013).
age-related macular degeneration (1 paper, 2023). Age-related loss of vision in the central portion of the retina (macula), secondary to retinal degeneration. "VPS54 is reported to be associated with Retinitis pigmentosa; IQGAP1 is reported to regulate choroidal vascularization in Age-Related Macular Degeneration; NMB is involved in RPE homeostasis regulation; MC5R is reported to regulate lacrimal gland function." (PMID 37359372, 2023).
cervical tumors (1 paper, 2021).
cognitive decline (1 paper, 2024). "This suggested cognitive decline occurs in rats with downregulated levels of MC5R expression." (PMID 39333746, 2024).
dyslexia (1 paper, 2010). A learning disorder characterized by an impairment in processing written words. "Along with already published biological evidence, MC5R, DYM and NEDD4L make attractive candidates for dyslexia susceptibility genes." (PMID 21060895, 2010).
generalized anxiety disorder (1 paper, 2022). An anxiety disorder characterized by excessive and difficult-to-control worry about a number of life situations. "It was reported that MC5R antagonist could treat the depressive or generalized anxiety disorder." (PMID 35619902, 2022).
glomerular disease (1 paper, 2022). "Recent evidence suggests that MC5R is expressed in human glomeruli and the change in its expression is associated with glomerular diseases, such as FSGS and membranous nephropathy." (PMID 35721571, 2022). "However, despite these findings, the role of MC5R in the pathogenesis of glomerular disease remains elusive." (PMID 35721571, 2022).
heart failure (1 paper, 2024). Inability of the heart to pump blood at an adequate rate to meet tissue metabolic requirements. "Intriguingly, MC5-R is expressed in the mouse heart and the dimer form of MC5-R protein was increased in the LV of hypertrophied heart with normal ejection fraction, while in heart failure, the amount of MC5-R dimer form was significantly reduced." (PMID 38454158, 2024). "Taken together, these findings suggest that pharmacological targeting of MC5-R signaling could provide therapeutic benefits in the management of heart failure." (PMID 38454158, 2024). "Thus, the progression from compensated hypertrophy to heart failure led to parallel changes in cardiac MC5-R expression and α-MSH level, suggesting that exhaustion of α-MSH production simultaneously compromises the integrity of MC5-R." (PMID 38454158, 2024). "Finally, to evaluate the therapeutic potential of targeting MC5-R for the management of heart failure, we employed the TAC-model in C57Bl/6N mice that are more prone to develop TAC-induced heart failure and treated the mice with PG-901 at two different dose levels (0.005 or 0.5 mg/kg/day)." (PMID 38454158, 2024). "Even if future research does not support the translation of MC5-R targeted drugs for treating human heart failure, the present findings predict a favorable cardiac safety profile for drugs that have agonistic activity at MC5-R." (PMID 38454158, 2024).
inflammatory bowel disease (1 paper, 2025). A spectrum of small and large bowel inflammatory diseases of unknown etiology. "The latest clinical research data indicate that the expression of MC3R and MC5R is significantly increased in inflamed mucosa of inflammatory bowel disease (IBD) patients compared to normal mucosa." (PMID 40078988, 2025).
ischemic cardiomyopathy (1 paper, 2024). Ischemic cardiomyopathy is a cardiomyopathy in which a weakness in the muscle of the heart due to inadequate oxygen delivery to the myocardium with coronary artery disease being the most common cause. "We first quantified the mRNA levels of MC5R in the LV samples from control subjects and from patients with end-stage dilated (DCM) or ischemic cardiomyopathy (ICM)." (PMID 38454158, 2024).
Menstrual disorder (1 paper, 2015). Category of disorders related to menstruation. "Moderate MC5R expression on ECs and VSMCs of the endometrial vasculature also suggests that ACTH may have a direct effect on vascular development or remodelling, and therefore contribute to the menstrual disorders observed after administration of synthetic ACTH." (PMID 26223677, 2015).
uveal melanoma (1 paper, 2021). A melanoma derived from melanocytes of the uveal tract. "The TCGA-UVM data confirmed that MC1R, MC4R, and MC5R were expressed in uveal melanoma, with MC1R exhibiting the highest expression level (data not shown)." (PMID 34436011, 2021).
tumor (13 papers, 2012 to 2026). "By constructing Mc5r-systemic or conditional-deficient mice for the tumor-bearing experiment, we found that Mc5r deficiency significantly enhanced antitumor immunity and inhibited the development of different tumor types." (PMID 39872954, 2023). "Pituitary derived α-MSH was reported to promote myelopoiesis and immunosuppression to accelerate tumor growth via activating MC5R, since MC5R is highly expressed in bone marrow progenitors." (PMID 40473594, 2025). "α-MSH acted on melanocortin 5 receptor (MC5R)-expressing bone marrow progenitors to promote myelopoiesis, myeloid cell accumulation, and immunosuppression, which could promote tumor growth." (PMID 39872954, 2023). "In addition, blocking MC5R with antagonists could inhibit tumor growth and exert synergistic effects with immune checkpoint drugs." (PMID 39872954, 2023).
cancer (4 papers, 2012 to 2024). A tumor composed of atypical neoplastic, often pleomorphic cells that invade other tissues. "Since the activation of MC5R stimulates the proliferation of MDSCs from the bone niche, the human cohorts with natural loss of function of MC5R may have decreased incidence of all types of cancers with low plasma level of circulating MDSCs." (PMID 37342674, 2023). "Of these 16 dmCpGs, 14 were hypermethylated whilst two, cg16709294 (SFRS5) and cg14179575 (MC5R), were hypomethylated in cancer compared with benign samples." (PMID 39095452, 2024). "As a promising adjuvant GPCR target for treating human cancer, future studies should be focused on the clinical improvement of current immunotherapy by concurrent pharmacological modulation of MC5R signaling." (PMID 37342674, 2023). "Therefore, in addition to cancer immunotherapy, clinical development of MC5R as a pharmacological target for the treatment of myelopoiesis-associated disorders deserves extra attention." (PMID 37342674, 2023). "Direct administration of inhibitory antibody, polypeptide antagonist, or small molecule negative allosteric modulator of MC5R might improve cancer therapies through PD1/PDL1, CTLA4, or chimeric antigen receptor T (CAR-T) cells." (PMID 37342674, 2023).
inflammation (2 papers, 2017 to 2023). Aberrant reaction of the microcirculation characterized by movement of fluid and leukocytes from the blood into extravascular tissues. "Furthermore, Foxo4 only reversed the upregulation of MC5R and Leptin (P<0.05), and the downregulation of Foxo4 and IL-6 by αMSH in mRNA level (P<0.05), suggesting that αMSH may inhibit adipocyte inflammation partly via Foxo4 transcriptional regulation." (PMID 28514752, 2017). "Therefore, we hypothesized that during the inflammation of the lungs of the body, systemic production of α-MSH increased, and negatively regulates the aggravation of lung inflammation through MC5R on ILC2s, thereby maintaining the homeostasis of the airway inflammation." (PMID 37699899, 2023). "Importantly, conditional deletion of the Mc5r gene led to higher ILC2 responses and severe lung inflammation in mice." (PMID 37699899, 2023).
kidney disease (1 paper, 2022). "Although glomerular expression of MC5R has been repeatedly described in rodents and humans, the role of MC5R in kidney disease is unknown." (PMID 35721571, 2022).
MC5R also shares sentences with these, for which no sentence is quoted: breast carcinoma (3 papers); glioma (2); type 2 diabetes (2); alopecia areata (1); autoimmune disease (1); breast tumors (1); cardiovascular diseases (1); congestive heart failure (1); dry eye (1); ductal carcinoma in situ (1); hair diseases (1); Hyperglycemia (1); infection (1); injury (1); kidney failure (1); lung carcinoma (1); nephrosis (1); osteoporosis (1); Proteinuria (1); psoriasis (1); retina degeneration (1); Retinal dystrophy (1); retinitis pigmentosa (1); retinopathy (1); viral infection (1); vitiligo (1).